CP (ceruloplasmin)
Diseases named in the same sentence as CP in open-access papers (continued):
Sharing a sentence is not in itself a finding about the gene and the disease.
ischemic cardiomyopathy (1 paper, 2013). Ischemic cardiomyopathy is a cardiomyopathy in which a weakness in the muscle of the heart due to inadequate oxygen delivery to the myocardium with coronary artery disease being the most common cause. "Mean CP levels were 250.01 ± 47.54, 313.06 ± 73.60, and 328.80 ± 98.91 mg/L, for patients in the control, ischemic cardiomyopathy, and nonischemic cardiomyopathy groups, respectively." (PMID 23781119, 2013).
Jaundice (1 paper, 2013). Yellow pigmentation of the skin due to bilirubin, which in turn is the result of increased bilirubin concentration in the bloodstream. "On the other hand, the antioxidant enzymes GR and CP activities were significantly increased in P. vivax infected patients (with or without jaundice) compared with the control group." (PMID 24020374, 2013).
Klebsiella Infections (1 paper, 2022). Infections with bacteria of the genus KLEBSIELLA. "Immune complex-mediated activation of the CP is recognised as an important mechanism in the control of Klebsiella infection." (PMID 35572551, 2022).
leukocytosis (1 paper, 2022). "Most CP (89.47%, 17/19) and OP (65.85%, 27/41) bitches presented with leukocytosis." (PMID 36185522, 2022).
Liver abscess (1 paper, 2019). A circumscribed area of pus or necrotic debris in the liver. "Increased expression of normally low-expressing CP genes was also found in trophozoites from amoebic liver abscess." (PMID 30866809, 2019).
lung disease (1 paper, 2020). "Its potential role in lung disease development has been shown in a murine model of PAH, and elevated concentrations of CP in SSc have been observed as early as 1975." (PMID 32630589, 2020).
lymphedema (1 paper, 2012). Excess fluid collection in tissues, causing swelling. "To determine the association of microbial translocation and related markers with filarial lymphedema, we measured the plasma levels of LPS, LPB, EndoCAb, and sCD14 in CP Ag+, INF, CP Ag−, and EN." (PMID 22685406, 2012).
malabsorption syndrome (1 paper, 2021). A syndrome resulting from the inadequate absorption of nutrients in the small intestine. "Immunoglobulin and lymphocyte loss frequently accompanies protein loss, such as albumin, lipoprotein, fibrinogen, transferrin, and ceruloplasmin, through the intestinal tract, in patients with malabsorption syndrome." (PMID 37744114, 2021).
medullary thyroid carcinoma (1 paper, 2020). "Since some studies have revealed the association between the development of thyroid cancer and adipokines, this study aimed to investigate this relationship between medullary thyroid cancer and ceruloplasmin." (PMID 32309247, 2020). "The present study was done based on the hypothesis which some adipokines such as ceruloplasmin could be related to medullary thyroid carcinoma." (PMID 32309247, 2020).
meningioma (1 paper, 2014). A generally slow growing tumor attached to the dura mater. "Western blot analyses of three differentially expressed targets proteins; apolipoprotein E, ceruloplasmin and clusterin were carried out using a subset of healthy control and meningiomas samples (MGI, MGII and MGIII)." (PMID 25413266, 2014). "Western blot results indicated up-regulation of Apo E, CLU and CP in meningioma patients compared to the healthy controls (p < 0.005 in a Mann Whitney U-test)." (PMID 25413266, 2014).
metastatic cancer (1 paper, 2021). A carcinoma which has spread from the original site of growth to another anatomic site. "We also observed CDH2, CP, HP, TF, and SERPINA5 were upregulated in liver metastatic cancer tissues and downregulated in primary cancer tissues; whereas SPARCL1 exhibited the opposite expression pattern." (PMID 34422629, 2021). "Therefore, in the observed tissues, SPARCL1 was most highly expressed in normal colorectal tissues, and CDH2 had the highest expression in normal liver tissues and liver metastatic cancer tissues, while CP, HP, TF, and SERPINA5 with the most highly expressed in normal liver tissues." (PMID 34422629, 2021).
methemoglobinemia (1 paper, 2020). An inherited or acquired condition characterized by abnormally increased levels of methemoglobin in the blood. "Copper is then bound rapidly from the gastrointestinal tract by carrier proteins, ceruloplasmin and albumin, and transported to the liver and other tissues, where it can cause hepatotoxicity, methemoglobinemia and rhabdomyolysis." (PMID 32926692, 2020).
mood disorder (1 paper, 2023). A cognitive disorder a disturbance in which the person's mood is hypothesized to be the main underlying feature. "Further, it should be noted that ceruloplasmin, a major copper transporter in the human organism, was observed to be increased in patients suffering from mood disorders." (PMID 37894749, 2023).
Mycoplasma infection (1 paper, 2020). "Together, the results indicate that exosomal miRNAs derived from MG‐infected CP‐II cells play a complex role in signalling pathways and regulating the inflammatory reactions, which provides the theoretical basis, direction for the prevention and treatment of Mycoplasma infection in poultry." (PMID 32307881, 2020).
nonischemic cardiomyopathy (1 paper, 2013). Forms of cardiomyopathy that are not related to known coronary artery disease. "Ceruloplasmin was significantly elevated in patients with ischemic or nonischemic cardiomyopathy and had linear correlation with C-reactive protein and LVEF." (PMID 23781119, 2013). "We concluded that CP levels were significantly high in patients with ischemic or nonischemic cardiomyopathy and had a positive linear correlation with C-reactive protein and a negative linear correlation with LVEF." (PMID 23781119, 2013). "In nonischemic cardiomyopathy patients, CP levels were significantly different among NYHA II, NYHA III, and NYHA IV groups (291.81 ± 56.28, 318.54 ± 91.98, and 375.03 ± 120.11, P < 0.05)." (PMID 23781119, 2013). "Then we compared the CP levels of different NYHA levels in ischemic and nonischemic cardiomyopathy groups, respectively." (PMID 23781119, 2013).
ocular hypertension (1 paper, 2017). Abnormally high intraocular pressure. "Ocular hypertension also caused upregulations in the iron-regulating protein ceruloplasmin, the anaerobic glycolytic enzyme lactate dehydrogenase, and the transcription factors cFos and p-cJun." (PMID 28883787, 2017). "Ceruloplasmin displays a pattern of immunolabeling within the control and treated (data not shown) ONH that is characteristic of astrocytes, suggesting that the increase in protein expression following ocular hypertension derives from upregulation by this cell type." (PMID 28883787, 2017).
Oral leukoplakia (1 paper, 2025). A thickened white patch on the oral mucosa that cannot be rubbed off. "Serum ceruloplasmin levels were higher in all oral leukoplakia, OSMF, and OSCC, as compared to controls, and the differences were statistically significant." (PMID 40256126, 2025).
orofacial cleft (1 paper, 2024). A disorder of facial skeleton that is characterized by cleft lip and/or cleft palate that result in feeding, speech and hearing problems caused by failures during development. "The other types of orofacial clefts were characterized by a low (CBT, CP-FRI or CP-FLI, CSPo-FI, and CRT or CLT + CP-FRI or CP-FLI) or null (CPo-FC, CPo-FI, CP-FRC or CP-FLC, DG-G, and CP-FRI or CP-FLI + CPo-FI) frequency of staphylococcal oral colonization." (PMID 39338954, 2024).
osteogenesis imperfecta (1 paper, 2020). Osteogenesis imperfecta (OI) comprises a heterogeneous group of genetic disorders characterized by increased bone fragility, low bone mass, and susceptibility to bone fractures with variable severity. "Tests for metabolic bone disease such as measuring levels of calcium, phosphorus, alkaline phosphatase (ALP), parathyroid hormone (PTH), vitamin D, copper, and ceruloplasmin should be done routinely, and testing for genetic disease, e.g., osteogenesis imperfecta, should be considered." (PMID 33308191, 2020).
pantothenate kinase-associated neurodegeneration (1 paper, 2013). "In addition to the core syndromes of pantothenate kinase-associated neurodegeneration (PKAN, NBIA1) and PLA2G6-associated neurodegeneration (PLAN, NBIA2), several other genetic causes have been identified (including FA2H, C19orf12, ATP13A2, CP and FTL)." (PMID 23814539, 2013).
paragonimiasis (1 paper, 2021). A parasitic infection caused by trematodes of the Paragonimus genus. "In this pilot evaluation, CP-6 and MYO-1 had a sensitivity of 100% with sera from paragonimiasis patients vs sensitivities of 76, 41, and 24% for MDP, EYF, and CYS-2, respectively." (PMID 33415393, 2021).
peripartum cardiomyopathy (1 paper, 2015). Peripartum cardiomyopathy (PPCM) is an idiopathic, potentially fatal form of dilated cardiomyopathy that develops during the final month of pregnancy or within five months after delivery. "The study aimed to determine if selenium deficiency, serum ceruloplasmin and traditional birth practices are risk factors for peripartum cardiomyopathy (PPCM), in Kano, Nigeria." (PMID 25853263, 2015).
pneumococcal pneumonia (1 paper, 2024). A febrile disease caused by STREPTOCOCCUS PNEUMONIAE. "Additionally, whether the immunization protocols, including Cp and CP-derived BLPs, together with the pneumococcal vaccines can enhance the resistance to secondary pneumococcal pneumonia induced after inflammatory lung damage mediated by the activation of Toll-like receptor 3 (TLR3) was assessed." (PMID 38675794, 2024).
pneumoconiosis (1 paper, 2017). An occupational lung disorder caused by inhalation of dust particles. "Serum ceruloplasmin (CP) is a glycoprotein containing copper, reflecting the level of oxidative stress and playing a critical role in the process of collagen fibrils formation, which is associated with the fiber lesions in pneumoconiosis." (PMID 29280967, 2017).
polyarthritis (1 paper, 2005). "The present study shows that exposure to an environmental agent capable of inducing an RA-like polyarthritis in rodents – mineral oil – is associated with an increased risk for RF+ RA and anti-CP+ RA in man." (PMID 16277683, 2005).
primary brain tumors (1 paper, 2023). "As the early 1984s, it has been shown in patients with primary brain tumors an increase in serum copper and CP levels that potentially associated with decreased catabolism of CP." (PMID 38006431, 2023).
primary cardiomyopathy (1 paper, 2020). "The findings suggest that SDMA, LRG1, SAA, and ceruloplasmin are promising novel biomarkers for CHF caused by primary cardiomyopathy in cats." (PMID 32395893, 2020).
primary Sjögren’s syndrome (1 paper, 2025). "Moreover, studies have shown that plasma exosomes from patients with primary Sjögren’s syndrome—represented by ceruloplasmin (CP) and transferrin (TF)—contain epithelial cell-derived proteins involved in ferroptosis." (PMID 40934008, 2025).
Prostate tumors (1 paper, 2009). "Prostate tumors used to generate CP tissue expression datasets." (PMID 20021671, 2009).
protein deficiency (1 paper, 2019). "The lower relative protein and AA deposition rate together with the greater relative fat deposition rate in the EB of LP-EM compared with C-EM showed that the 20% dietary restriction of CP, lysine, methionine, tryptophan and threonine points toward a protein deficiency." (PMID 29789036, 2019).
Pruritus (1 paper, 2023). Pruritus is an itch or a sensation that makes a person want to scratch. "Interestingly, CBD also induced comparable recruitment of immune cells around the hair follicles, although we did not observe any overt signs of pruritus in these animals, indicating CBD is not immunologically inert, and the type of immune cells recruited by CBD and β-CP and need phenotyping." (PMID 37762646, 2023).
psychiatric disturbances (1 paper, 2020). "Although it remains unclear whether there is a causal relationship between levels of ceruloplasmin and psychiatric disturbances, ceruloplasmin dysfunction is thought to disrupt copper homeostasis." (PMID 33062249, 2020).
psychosis (1 paper, 2015). "Elevated free copper contributes to neuronal damage in circuits responsible for sensory-processing and copper levels may also be influenced by reduced ceruloplasmin (copper binding protein) levels which has been linked to psychosis." (PMID 25729574, 2015).
pulmonary hypertension (1 paper, 2016). Increased pressure within the pulmonary circulation due to lung or heart disorder. "In future studies employing the CP mutation to study modest HIF dysregulation, targeting this mutation specifically to cardiac myocytes could obviate the influence of pulmonary hypertension." (PMID 27422990, 2016).
pyometra (1 paper, 2024). "SPARCLTM assays have been used to quantify haptoglobin, C-reactive protein, AGP and Ceruloplasmin in the plasma of healthy dogs and dogs with pyometra." (PMID 38793672, 2024).
respiratory infections (1 paper, 2024). "In addition to the liver, almost the same amount of ceruloplasmin is synthesised in the lungs, where its serum concentrations rapidly increase during respiratory infections and heart diseases." (PMID 38254360, 2024).
sarcoma (1 paper, 2024). A usually aggressive malignant neoplasm of the soft tissue or bone. "In both CP and CPN mice, we also observed predominantly abdominal sarcomas and carcinomas." (PMID 38335300, 2024).
sarcopenia (1 paper, 2025). Progressive decline in muscle mass due to aging which results in decreased functional capacity of muscles. "Upregulation of CP in sarcopenic muscle may represent a compensatory response to oxidative stress and disturbed metal metabolism; prior work from our group implicating cuproptosis in sarcopenia provides a coherent link among CP expression, redox balance, and metal homeostasis." (PMID 41488001, 2025).
staphylococcal infection (1 paper, 2020). An infection caused by Staphylococcus. "The aim of the study was to determine the expressions of SAA3, HP, and CP genes in MECs and CLECs during chronic subclinical mastitis caused by CoPS and CoNS vs. bacteria-free udder samples to compare the immune response of both tissues to staphylococcal infection." (PMID 32867772, 2020).
sterility (1 paper, 2008). "Progeny resulting from crosses of aposymbiotic CPT males demonstrates that the observed sterility in CP crosses is due to the Wolbachia infection." (PMID 18235849, 2008).
thrombosis (1 paper, 2018). "By contrast, blood flow, which was reduced to 90% at the beginning of the induced thrombosis in the artery, quickly recovered to 50% within a few minutes, and then to 70, 80, and 90% within a couple hours in CP-Tg mice, which survived the procedure." (PMID 29374184, 2018).
thrombotic disease (1 paper, 2020). The formation of a blood clot in the lumen of a vessel or heart chamber; causes include coagulation disorders and vascular endothelial injury. "CPSM extract is a combination of extracts from the fruit of CP and the root of SM and is utilized in the management of thrombotic diseases." (PMID 33329023, 2020).
thyrotoxicosis (1 paper, 2022). A hypermetabolic syndrome caused by the elevation of thyroid hormone levels in the serum. "Above all, Alb, Trf, CP, and Sepp1 played important role in maintaining ion homeostasis and innate immunity, their downregulation seriously affected the defense ability of thyrotoxicosis mice." (PMID 35720307, 2022). "In addition, copper and selenium homeostasis also played important role in innate immunity, and their transport proteins Ceruloplasmin (CP) and selenoprotein P (Sepp1) were downregulated in thyrotoxicosis mice." (PMID 35720307, 2022).
Tics (1 paper, 2021). Repeated, individually recognizable, intermittent movements or movement fragments that are almost always briefly suppressible and are usually associated with awareness of an urge to perform the movement. "When endeavoring to rule out secondary etiologies, more than 90% of respondents reported using neuroimaging to rule out contributory causes of tics in their patients, and 66% also ordered laboratory tests, for example, to search for acanthocytes or assess serum copper or ceruloplasmin." (PMID 34754602, 2021).
transient cerebral ischemia (1 paper, 2022). "Furthermore, differential effects of and changes in ceruloplasmin in the hippocampal CA1 region between adult and aged gerbils after transient cerebral ischemia were observed." (PMID 35806305, 2022).
uremia (1 paper, 2009). A clinical syndrome associated with the retention of renal waste products or uremic toxins in the blood. "In conclusion, the significant increase in levels of MDA, and the decrease in levels of protein thiols, CP, and copper in uremia patients when compared to controls, reconfirms the presence of stress in this patient population." (PMID 20352004, 2009).
uric acid stones (1 paper, 2025). "Notably, uric acid stones were characterized by elevated levels of ceruloplasmin, activated partial thromboplastin time (aPTT), and myoglobin." (PMID 40551898, 2025).
uveitis (1 paper, 2025). An inflammatory process affecting a part of or the entire uvea. "The variability in ceruloplasmin expression in uveitis is not yet fully understood, and further research is needed to clarify its significance." (PMID 41402737, 2025).
varicocele (1 paper, 2021). A condition characterized by the dilated tortuous veins of the spermatic cord with a marked left-sided predominance. "While the P1/P2 mRNA ratio in CP/CPPS has not been evaluated to date, previous studies found significant changes in the parameter in other urogenital conditions, such as significant elevations in patients with varicocele or increased rates of aberrant ratios in patients with bacterial infection." (PMID 34360620, 2021).
ventricular fibrillation (1 paper, 2017). A disorder characterized by an electrocardiographic finding of a rapid grossly irregular ventricular rhythm with marked variability in QRS cycle length, morphology, and amplitude. "In the reperfusion phase after cardioplegia a slight prolongation of TAT occurred in the CP- group, which was accompanied by an enhanced incidence of ventricular fibrillation." (PMID 28579963, 2017).